MDM2 (MDM2 proto-oncogene)
Diseases named in the same sentence as MDM2 in open-access papers (continued):
Sharing a sentence is not in itself a finding about the gene and the disease.
liposarcoma (continued). "We report a case initially diagnosed as undifferentiated sarcoma that was reclassified as intraperitoneal dedifferentiated liposarcoma showing an amplification of the MDM2 gene." (PMID 24279301, 2013). "MDM2 over-expression has been detected in approximately 80% of liposarcomas but only limited information is available about MDMX over-expression." (PMID 24330579, 2013). "Knockdown of YEATS4 in liposarcoma cell lines resulted in better in vitro anti-proliferative effects compared to MDM2." (PMID 24216990, 2013). "Histologic examination, ideally by an experienced soft tissue sarcoma pathologist, is best supplemented with molecular studies (e.g., MDM2 amplification by fluorescence in situ hybridization in WD/DD liposarcoma) for accurate diagnosis." (PMID 24216990, 2013). "There are two other cancers, dedifferentiated liposarcomas and lung adenocarcinomas that also show MDM2/CDK4 co-amplification in 90% and 4% of cases respectively." (PMID 24261984, 2013). "In well differentiated (WD) and dedifferentiated (DD) liposarcomas, amplification of MDM2 is seen in virtually all tumors and in fact, is a reliable method for clinical diagnosis." (PMID 24216990, 2013). "Both TSPAN31 and MDM2 were amplified in 8 of 11 liposarcoma samples, with MDM2 amplified alone in one additional tumour." (PMID 21253554, 2011). "Liposarcoma are characterized by more numerous spindle cells, presence of nuclear pleomorphism and MDM-2 amplification." (PMID 21739018, 2011). "Of relevant interest, an MDM2 antagonist RO5045337 is about to recruit for a Phase I trial in liposarcoma patients." (PMID 21253554, 2011). "About 80% of well-differentiated liposarcomas are characterized by ring or giant marker chromosomes derived from chromosome 12q13~q15, including MDM2, HGMA2, and other genes." (PMID 21403834, 2011). "Mdm-2 has been reported to be a useful marker in liposarcomas, but is less well studied in bone tumors." (PMID 19594492, 2009). "Most dedifferentiated liposarcomas are characterized by amplifications of MDM2 and CDK4 as part of the 12q amplicons involved in the formation of ring-chromosomes." (PMID 17359542, 2007). "CDK4 and MDM2 gene amplifications were identified in liposarcoma and osteosarcoma." (PMID 41562936, 2026). "For example, inflammatory well‐differentiated liposarcoma, a rare and locally aggressive retroperitoneal tumor, is defined by overexpression of mouse double minute 2 (MDM2) homolog and cyclin‐dependent kinases 4 (CDK4), with potential progression to dedifferentiated liposarcoma." (PMID 41262926, 2025). "However, the defining diagnostic test to differentiate between lipomas and ALT/well differentiated liposarcoma is the molecular demonstration by fluorescence in-situ hybridisation of amplification of the MDM-2 cell cycle oncogene." (PMID 38734790, 2025). "The majority of dedifferentiated liposarcomas show amplification of MDM2 and CDK4." (PMID 40002892, 2025). "Also, high amplification levels of MDM2 correlate with poor outcomes in patients with dedifferentiated liposarcoma." (PMID 40933567, 2025). "Unexpected MDM2 positivity was identified in 44% of tested cases, with one demonstrating gene amplification, suggesting potential overlap with atypical lipomatous tumor/well-differentiated liposarcoma (ALT/WDL)." (PMID 41527615, 2025).
liposarcoma (continued). "Key genes in this region, including MDM2, cyclase-associated protein (CPM), and solute carrier family 35 member E3 (SLC35E3), are significantly amplified and play a critical role in the progression of dedifferentiated liposarcoma." (PMID 39974236, 2025). "It was diagnosed as a well-differentiated liposarcoma with high MDM2 expression." (PMID 41179691, 2025). "There was no DDIT3 gene rearrangement or MDM2 gene amplification, and this can be utilized to differentiate this variant of liposarcoma from others." (PMID 40710010, 2025). "Fluorescence in situ hybridization for MDM2 amplification can be used to differentiate atypical/highly differentiated liposarcoma and dedifferentiated liposarcoma from PMPF, while CDK4 gene amplification helps to differentiate atypical/highly differentiated liposarcoma from PMPF." (PMID 40308488, 2025). "In another phase I trial of the MDM2 inhibitor alrizomadlin, conducted in patients predominantly diagnosed with advanced liposarcoma who had progressed on standard therapy, a partial response was achieved in 2 patients, while 10 patients experienced stable disease." (PMID 41299419, 2025). "An in vitro study has reported that miR-215-3p was upregulated (p < 0.05) 25-fold in liposarcoma cell lines, and this miRNA could increase MDM2 expression to decrease apoptosis activities in the liposarcoma cells." (PMID 39736850, 2025). "Thus, promotion of MDM2 expression, cell proliferation and invasion of the liposarcoma SW-872 cell line as well as inhibition of apoptosis by miR-215-5p is described in the literature." (PMID 38254762, 2024). "Therefore, the detection of CDK4/MDM2 by FISH or immunohistochemistry is necessary to exclude dedifferentiated liposarcoma." (PMID 38388450, 2024). "Furthermore, it is of note that well-differentiated liposarcoma arising as heterologous elements within a phyllodes tumors lack MDM2 amplification, therefore in this context attributed to borderline PT and not to a malignant variant." (PMID 38015260, 2024). "MDM2 amplification is present in 95% of well-differentiated and dedifferentiated liposarcomas, while benign lipomatous lesions do not show any amplification; thus, evaluating MDM2 status is crucial in the diagnosis of liposarcoma." (PMID 38275873, 2024). "It is important to note that many liposarcomas and other sarcomas, including intimal sarcoma with MDM2/CDK4 amplification, may exhibit cytoplasmic and/or nuclear expression of STAT6 without necessarily indicating a solitary fibrous tumor." (PMID 38275873, 2024). "Herein, we describe the case of a 91-year-old woman diagnosed with ovarian mucinous cystadenoma with a well-differentiated liposarcoma mural nodule, based on histological morphology, immunohistochemical examination, and MDM2/CDK4 fluorescence in situ hybridization (FISH) testing." (PMID 39220649, 2024). "This particularly applies to well-differentiated or dedifferentiated liposarcomas, which might not only benefit from MDM2 or CDK4 inhibitors, but also from anti-GLI1 therapies." (PMID 38275873, 2024). "Additionally, NCOR2 rearrangements have been reported as a likely incidental finding in a dedifferentiated liposarcoma with mdm2 proto-oncogene (MDM2) amplification." (PMID 38792018, 2024). "In our case, MDM2 was strongly positive favouring the diagnosis of dedifferentiated liposarcoma." (PMID 39011191, 2024). "In such cases, dedifferentiated liposarcoma might be a potential diagnosis due to the presence of MDM2/CDK4 amplification." (PMID 38275873, 2024). "MDM2 gene amplification has been found in nearly all cases of dedifferentiated liposarcoma." (PMID 37297833, 2023). "Indeed, the MDM2 amplification evaluation by FISH is a crucial and well-established assay for liposarcoma diagnostic work-up and, nowadays, is considered as a diagnostic gold standard." (PMID 36674856, 2023).
liposarcoma (continued). "The presence of MDM2 gene amplification, combined with the results from appropriate morphology and immunohistochemistry analyses, is useful diagnostically in the case of a liposarcoma in a rare location and will enable correct diagnosis and management." (PMID 38137051, 2023). "Specifically, MDM2 amplification is successfully identified in five out of six liposarcomas." (PMID 37627196, 2023). "Reducing MDM2 in cells can drive them into a more stable senescent state, and this effect has been observed in several types of cancer, including well-differentiated and dedifferentiated liposarcoma, breast cancer, lung cancer, and glioma." (PMID 37297833, 2023). "The inhibition of HDAC2 decreased the expression of MDM2 and induced apoptosis in liposarcoma." (PMID 36968022, 2023). "Additionally, dedifferentiated liposarcoma has been uniquely characterized by an amplification of MDM2." (PMID 36980578, 2023). "In addition, well-differentiated and dedifferentiated liposarcomas (n = 10) were all characterized by MDM2/CDK4 co-amplification." (PMID 35053600, 2022). "This binary classification is probably oversimplifying, and it may be misleading, for instance dedifferentiated liposarcoma is characterized by a driver alteration (MDM2 amplification), but it also has a highly rearranged genomic profile." (PMID 35626152, 2022). "List of clinical trials investigating MDM2 inhibition in liposarcomas or other solid tumors." (PMID 36439412, 2022). "Recurrent alterations identified were often unique to specific sarcoma subtypes; CDK4/MDM2 amplifications were identified in all but one dedifferentiated liposarcoma, ASPSCR1-TFE3 fusions in all patients with alveolar soft part sarcoma, and fusions involving EWSR1 in all patients with SBRCT." (PMID 35710741, 2022). "Interestingly, two cases of dedifferentiated liposarcoma and two cases of well-differentiated liposarcoma harbored the characteristic MDM2 amplification as a co-occurrent molecular alteration." (PMID 36741731, 2022). "Additionally, our study supports future research into liposarcoma therapies targeting MDM2-mediated metabolic pathways which enable cells to grow despite oxidative and nutrient stress." (PMID 36158671, 2022). "However, three cases diagnosed as pleomorphic sarcomas were reclassified as dedifferentiated liposarcomas after a positive MDM2 FISH." (PMID 36164527, 2022). "Major cargos in liposarcoma EVs include MDM2 DNA and specific miRNAs (miR‐25‐3p, mir‐92a‐3p)." (PMID 36043432, 2022). "For example, MDM2 amplification is present in most dedifferentiated liposarcomas and typically co-amplified with CDK4 and/or HMGA2, synovial sarcomas (SS) are often characterized by SS18–SSX fusions, and presence of MYOD1 mutations indicate spindle cell/sclerosing rhabdomyosarcoma." (PMID 35053600, 2022). "Second, The Cancer Genome Atlas analysis of soft tissue sarcomas demonstrated that dedifferentiated liposarcoma, conventionally classified by the presence of MDM2 amplification, formed two methylation groups which corresponded to significantly different clinical outcomes." (PMID 33949149, 2021). "The dedifferentiated liposarcomas are characterized by mouse double minute 2 (MDM2) and cyclin-dependent kinase 4 (CDK4) amplifications, and the CDK4 inhibitor, abemaciclib, is currently under investigation; an encouraging 12-week PFS of 76% in a phase II nonrandomized trial has been reported." (PMID 34207243, 2021). "This is in line with previous studies blocking MDM2 by Nutlin in liposarcomas, and may partly explain the good responses." (PMID 33690666, 2021). "Hence, this data identifies MDM2 and serine metabolism dependency as potential therapeutic targets for liposarcoma." (PMID 33801846, 2021).
liposarcoma (continued). "Immunohistochemically, the combination markers of cyclin-dependent kinase 4 (CDK4) and human murine double minute 2 (MDM2) were useful in the diagnosis of dedifferentiated liposarcoma, and there is strong correlation of marker expression with gene amplification status." (PMID 33422117, 2021). "Notably, MDM2 positivity by immunohistochemistry has been reported in cases of uterine leiomyosarcoma and primary liposarcoma of the uterus." (PMID 32352245, 2020). "The MDM2 gene is amplified in dedifferentiated liposarcoma (DDLPS)." (PMID 32806555, 2020). "Indeed, identifying synergistic combinations is crucial to developing successful MDM2 antagonist-based therapeutic strategies for liposarcoma." (PMID 32806555, 2020). "The unusual presentation of disseminated intraperitoneal disease coupled with the heavy inflammatory infiltrate served as a diagnostic pitfall and the diagnosis of a dedifferentiated liposarcoma was not apparent until the MDM2 FISH was performed." (PMID 31280066, 2019). "Significantly lesser marker chromosomes similar to those typically seen in atypical lipomas, and MDM2 in well-differentiated liposarcoma, are seen, an important distinction between these tumors, which may closely morphologically resemble each other." (PMID 31247518, 2019). "Amplification of the MDM2 gene is demonstrated in 95% of liposarcomas by FISH." (PMID 31280066, 2019). "The evidence regarding MDM2 inhibitors as a treatment for liposarcoma is limited to preclinical data and a phase I trial, but the double inhibition by MDM2 and CDK4 might be synergic, which would be worth evaluating." (PMID 29510588, 2018). "Hence, at this time the main utility of targeted sequencing in WD/DD liposarcoma patients using commercially available panels such as FM would be to identify patients for clinical trials testing agents that target the MDM2 and/or the CDK4 pathway." (PMID 29731991, 2018). "Interestingly, eight patients (two DD liposarcoma, one cellular WD liposarcoma and five with conventional WD liposarcoma) received an MDM2 inhibitor on a phase I clinical trial based on the molecular sequencing data." (PMID 29731991, 2018). "Six patients with liposarcoma were treated on phase I protocol with an MDM2 inhibitor." (PMID 30237864, 2018). "MDM2 amplification is actionable in liposarcoma (OncoKB level 3)." (PMID 30442178, 2018). "Specifically, CDK4 and MDM2 were frequently amplified in liposarcoma and osteosarcoma." (PMID 29416732, 2018). "Interestingly, all six patients who were enrolled in an MDM2 inhibitor trial in our study had liposarcoma." (PMID 30237864, 2018). "On the other hand, even in a disease such as liposarcoma where > 60% of patients have MDM2 amplification, the RR is relatively low, which may be due to the presence of co-alterations." (PMID 30148248, 2018). "Additionally, miR-26a-2, which is located near the MDM2 gene region is overexpressed in well- and dedifferentiated liposarcomas." (PMID 28895916, 2017). "In almost 90% of well- and dedifferentiated liposarcomas, an amplification of the 12q13-q22 gene region is present, as well as an overexpression of mouse double minute 2 homolog (MDM2) and cyclin dependent kinase 4 (CDK4), proteins characteristic of these liposarcoma subtypes." (PMID 28895916, 2017).
liposarcoma (continued). "In addition to being a diagnostic utility, detection of MDM2 amplification and CHOP rearrangement impact liposarcoma treatments that use selective MDM2 inhibitors and blockers of trans-activating ability of FUS-CHOP fusion protein." (PMID 29531545, 2017). "MDM2 amplification is a further target in the treatment of WD/DD liposarcoma." (PMID 29250486, 2017). "Efficacy of the first-generation MDM2 antagonist Nutlin-3a in cancers such as liposarcomas that express MDM2-B has been investigated, however, responses were heterogeneous with no promising results of Nutlin3a treatment achieved in MDM2-B expressing liposarcomas." (PMID 29065514, 2017). "Chromosomal breaks of the HMGA2 locus have been described in several benign mesenchymal tumors including lipomas and uterine leiomyomas, and HMGA2 amplification was shown in several soft tissue malignancies including liposarcomas where it is almost always co-amplified with MDM2." (PMID 27662657, 2016). "Distinguishing an atypical lipomatous tumor/well-differentiated liposarcoma from a benign lipomatous tumor on morphology alone can be difficult and there is an established role for MDM2 fluorescent in situ hybridization studies in making this differential diagnosis." (PMID 26987706, 2016). "The proto-oncogenes CDK4 and MDM2 are both amplified in well-differentiated liposarcoma." (PMID 27074562, 2016). "While no specific chromosomal translocations have been identified in well differentiated/dedifferentiated liposarcomas, amplification of MDM2 and CDK4 is very frequent in these subtypes, and their identification may be useful diagnostically." (PMID 25927975, 2015). "Dedifferentiated liposarcoma may mimic undifferentiated pleomorphic sarcoma, particularly in biopsy specimens; demonstration of amplification of mdm-2 confirms the diagnosis of liposarcoma." (PMID 26358059, 2015). "Interestingly, previous studies, molecular abnormalities associated with liposarcoma have been reported, such as amplification of the mdm2 gene and overexpression of the mdm2 protein emerging as the most frequent abnormality in dedifferentiated liposarcoma." (PMID 24695632, 2014). "Amplification of MDM2 is characteristic for well differentiated and dedifferentiated liposarcomas." (PMID 25126005, 2014). "This characterization may also provide insights into the cellular function of MDMX in liposarcomas and may guide future functional studies to evaluate the utility of novel, dual MDM2/MDMX blocking compounds in the treatment of STS." (PMID 24330579, 2013). "In addition, we analyzed the mRNA level of MDM2 gene, a key feature of well-differentiated liposarcoma, and found that MDM2 expression was markedly elevated in the adipose tumors in IL-22-TG mice fed with HFD (data not shown)." (PMID 21897855, 2011). "Therefore, assessing for amplification of MDM2 by FISH or immunohistochemistry is a powerful tool in supporting the diagnosis liposarcoma secondarily involving the GI tract." (PMID 21403834, 2011). "Subsequent surgical resection revealed a dedifferentiated liposarcoma (DDLPS) characterized by extensive necrosis and associated acute inflammation, with identification of a well-differentiated component and murine double minute 2 (MDM2) positivity by immunohistochemistry." (PMID 42137702, 2026). "Importantly, the absence of cytologic atypia, lipoblasts, and mitotic activity supports a diagnosis of lipoma and helps exclude atypical lipomatous tumor/well-differentiated liposarcoma, but when morphology is equivocal, ancillary MDM2/CDK4 testing is recommended." (PMID 41367444, 2025). "One common type of MDM2 alteration is its amplification, which often results in MDM2 protein overexpression and is observed in various malignancies, and the incidence of MDM2 amplification ranges from 0% (anaplastic and papillary carcinoma of thyroid) to 63.6% (liposarcoma)." (PMID 38281981, 2024).